SUPT7L (SPT7 like, STAGA complex subunit gamma)
Description:
As a component of the STAGA transcription coactivator-HAT complex, is involved in transcriptional regulation.
Synonyms: STAF65gamma; KIAA0764; SPT7L; STAF65; FZPS; STAF65(gamma); STAF65G; SUPT7H
Tractability: PROTAC: UniProt records ubiquitination sites on it; ubiquitination databases record sites on it; its protein half-life has been measured.
Gene: Protein-coding gene on chromosome 2 (27,650,809 to 27,663,841, reverse strand). Ensembl gene ENSG00000119760.
Subcellular location: Nucleus
Subcellular location (Human Protein Atlas): Nucleoplasm
Pathways (Reactome):
Chromatin organization: HATs acetylate histones
Gene Ontology:
Molecular function: protein binding; transcription coactivator activity; protein heterodimerization activity
Biological process: maintenance of protein location in nucleus; positive regulation of DNA-templated transcription; regulation of DNA repair; regulation of RNA splicing
Cellular component: nucleoplasm; nucleus; SAGA complex
Genetic constraint (gnomAD): Loss-of-function variants: 15 observed, 37.39 expected, observed/expected ratio (o/e) 0.4, 90% interval 0.27 to 0.62. The upper end of that interval is the gene's LOEUF score, 0.62, which puts it in group 2 of 6, group 1 being the genes least tolerant of losing a copy. Missense variants: 434 observed, 549.71 expected, observed/expected ratio (o/e) 0.79, 90% interval 0.73 to 0.86. Synonymous variants: 168 observed, 197.52 expected, observed/expected ratio (o/e) 0.85, 90% interval 0.75 to 0.97.
Homologues: Orthologues: chimpanzee SUPT7L (100% identical), macaque SUPT7L (99% identical), dog SUPT7L (98% identical), pig SUPT7L (96% identical), rabbit SUPT7L (96% identical), guinea pig SUPT7L (96% identical), rat Supt7l (95% identical), mouse Supt7l (95% identical), tropical clawed frog supt7l (79% identical), zebrafish supt7l (71% identical).
Diseases named in the same sentence as SUPT7L in open-access papers:
SUPT7L is named in the same sentence as 6 diseases in open-access papers, as found by Europe PMC text mining. Sharing a sentence is not in itself a finding about the gene and the disease. The quoted sentences say what the papers report.
generalized lipodystrophy (1 paper, 2024). Almost complete absence of subcutaneous and/or visceral adipose tissue. "In the present study we identified a missense and a frameshift variant in a compound heterozygous state in SUPT7L in a boy with intrauterine growth retardation, generalized lipodystrophy, and additional progeroid features." (PMID 38592547, 2024). "Here we report on the identification of compound heterozygous variants in SUPT7L, encoding a component of the STAGA complex, in an individual with generalized lipodystrophy, cataracts and a neonatal tooth, sharing features with Wiedemann-Rautenstrauch syndrome and other progeroid disorders." (PMID 38592547, 2024).
lipodystrophy (1 paper, 2024). A congenital or acquired disorder characterized by abnormal loss or redistribution of the adipose tissue in the body. "Recent studies have identified SUPT7L loss-of-function mutations in a patient exhibiting lipodystrophy and features associated with progeria, a condition of premature aging." (PMID 39222683, 2024). "Impairment of USP22 functions upon loss of SAGA integrity might also be related to the intrauterine retardation observed in the SUPT7L deficient lipodystrophy patient, as USP22 is required for placental vasculogenesis in mice." (PMID 39222683, 2024).
myeloma (1 paper, 2024). "Among the proteins not previously linked to MM were three members (TAF5L, SUPT7L and SUPT20H) of the SAGA complex, a posttranslational regulator of MYC transcriptional activity that is important for myeloma growth." (PMID 38942927, 2024).
SUPT7L also shares sentences with these, for which no sentence is quoted: influenza infection (1 paper); lung adenocarcinoma (1); tumour (1).